FGD6 (FYVE, RhoGEF and PH domain containing 6)
Description:
May activate CDC42, a member of the Ras-like family of Rho- and Rac proteins, by exchanging bound GDP for free GTP. May play a role in regulating the actin cytoskeleton and cell shape (By similarity).
Synonyms: ZFYVE24; FLJ11183
Tractability: PROTAC: ubiquitination databases record sites on it.
Gene: Protein-coding gene on chromosome 12 (95,076,749 to 95,217,482, reverse strand). Ensembl gene ENSG00000180263.
Subcellular location: Cytoplasm; Cytoplasm, cytoskeleton
Subcellular location (Human Protein Atlas): Vesicles
Gene Ontology:
Molecular function: protein binding; guanyl-nucleotide exchange factor activity; small GTPase binding; metal ion binding
Biological process: actin cytoskeleton organization; cytoskeleton organization; filopodium assembly; regulation of cell shape; regulation of GTPase activity
Cellular component: cytoplasm; Golgi apparatus; lamellipodium; ruffle; cytoskeleton
Genetic constraint (gnomAD): Loss-of-function variants: 79 observed, 137.94 expected, observed/expected ratio (o/e) 0.57, 90% interval 0.48 to 0.69. The upper end of that interval is the gene's LOEUF score, 0.69, which puts it in group 2 of 6, group 1 being the genes least tolerant of losing a copy. Missense variants: 1,389 observed, 1,691.8 expected, observed/expected ratio (o/e) 0.82, 90% interval 0.79 to 0.86. Synonymous variants: 509 observed, 591.03 expected, observed/expected ratio (o/e) 0.86, 90% interval 0.8 to 0.93.
Homologues: Orthologues: chimpanzee FGD6 (99% identical), macaque FGD6 (97% identical), dog FGD6 (87% identical), rabbit FGD6 (83% identical), pig FGD6 (80% identical), mouse Fgd6 (74% identical), rat Fgd6 (74% identical), guinea pig FGD6 (69% identical), tropical clawed frog fgd6 (54% identical), zebrafish fgd6 (41% identical), Caenorhabditis elegans exc-5 (15% identical), Caenorhabditis elegans frm-3 (6% identical). Paralogues in human: FGD5 (27% identical), FGD4 (16% identical), FGD1 (15% identical), FARP2 (14% identical), FARP1 (14% identical), FGD2 (13% identical), FGD3 (13% identical), ECT2L (9% identical), ARHGEF39 (6% identical), FRMD7 (5% identical).
Diseases named in the same sentence as FGD6 in open-access papers:
FGD6 is named in the same sentence as 18 diseases in open-access papers, as found by Europe PMC text mining. Sharing a sentence is not in itself a finding about the gene and the disease. The quoted sentences say what the papers report.
endometriosis (4 papers, 2020 to 2023). The growth of functional endometrial tissue in anatomic sites outside the uterine body. "By extending the genomic window around the consensus clusters by 2 kb to account for the promoter region, consensus clusters were found to overlap 11 endometriosis-associated SNPs across 6 genomic regions, including gene regions near FGD6, ARL14EP and CDC42." (PMID 37443771, 2023). "In relation to endometriosis, several studies have reported association of endometriosis risk with increased expression of VEZT and FGD6." (PMID 37443771, 2023). "Expression of several of these genes (LINC00339, CDC42, GDAP1, FGD6, SRP14) has been associated with risk of endometriosis previously." (PMID 37587191, 2023). "Risk variants for endometriosis on chromosome 6p25.1 are located in regulatory regions near oestrogen receptor 1 (ESR1) and both VEZT and FGD6 on chromosome 12q22 have roles in cell adhesion." (PMID 36304015, 2021).
breast cancer (2 papers, 2014 to 2019). A primary or metastatic malignant neoplasm involving the breast. "Additionally, we found genes highly expressed in breast cancer stroma in the Human Protein Atlas (EGR1, OSBPL8, FAM171A2, FGD6, and CEP131), or likely expressed in fibroblasts (MMP13), that are reported to play a role in breast cancer progression among the most important ones." (PMID 31505876, 2019).
macular degeneration (2 papers, 2020 to 2021). Loss of vision in the central portion of the retina (macula), secondary to retinal degeneration. "Life-extending SNPs near APOE, FOXO3 and FGD6 are all associated with increased measures of macular degeneration." (PMID 32678081, 2020). "Moreover, FGD6 mutations have also been related to a subtype of macular degeneration and FGD6 downregulation leads to actin disorganization." (PMID 34823607, 2021).
Aarskog–Scott syndrome (1 paper, 2024). "FGD6 is known from the Aarskog–Scott syndrome, characterized by short stature, facial abnormalities, skeletal and genital anomalies, and, in some cases, heart defects and a cleft lip." (PMID 38473885, 2024).
autism (1 paper, 2018). Persistent deficits in social interaction and communication and interaction as well as a markedly restricted repertoire of activity and interest as well as repetitive patterns of behavior. "FGD6 is an important paralog of the FGD1 gene which is associated with syndromic autism, where some patients are affected with a particular syndrome that presents as autism." (PMID 29888248, 2018).
coronary heart disease (1 paper, 2024). "Expression quantitative trait loci in FGD6 have been reported to be associated with coronary heart disease and to have an effect on CVD, potentially also reflected in variation in human lifespan." (PMID 38473885, 2024).
epilepsy (1 paper, 2021). A brain disorder characterized by episodes of abnormally increased neuronal discharge resulting in transient episodes of sensory or motor neurological dysfunction, or psychic dysfunction. "Noteworthy, among a list of 47 candidates, only a variant of unknown significance in FGD6 showed perfect segregation with all the affected members of this family leading us to hypothesize that it may have a role under a probable oligogenic model in the etiology of the epilepsy affecting this family." (PMID 34823607, 2021).
tumor (5 papers, 2014 to 2023). "Faciogenital dysplasia 6 (FGD6) was found to promote the proliferation, macropinocytosis, and tumor growth both in vitro and in vivo in pancreatic cancer." (PMID 37604837, 2023). "Herein, we found that GC patients with higher FGD6 in the tumor tissues had shorter overall survival and poorer clinical phenotypes." (PMID 34291059, 2021). "In addition, the mRNA expression of FGD6 was compared in 30 pairs of tumor and adjacent normal tissues, revealing its expression enhanced in tumor tissues compared with the adjacent normal tissues (p = 0.008)." (PMID 34291059, 2021). "Interestingly, the expression of ECT2, FGD6, MMP14, and SLC2A1 were statistically different in the patients with different tumor stage, which implied that ECT2, FGD6, MMP14, and SLC2A1 might be associated with the development of PC." (PMID 37604837, 2023). "EGR1, OSBPL8 (encoded by the gene KIAA1451), FAM171A2, FGD6, and CEP131 showed particularly high or largely exclusive staining in stromal cells, supporting the notion that indeed the expression profile of CAFs drives tumor classification in our random forest model." (PMID 31505876, 2019). "RNA transcriptomic analysis showed a gene significantly associated with the low cytoplasmic S100A2 group (AKT3, TAGLN, MYLK, FGD6 and ETFDH), which correlated with tumour development and progression." (PMID 37476187, 2023). "In our analysis from tumor versus “normal” germline samples, expression data demonstrated significant (p≤ 2.0-fold) down-regulation of LNX2 and FGD6 and up-regulation of CRISP1 in LGG." (PMID 25153720, 2014). "Additionally, the expressions of ECT2, FGD6, MMP14, and SLC2A1 were related to the staging of the tumor." (PMID 37604837, 2023).
cancer (1 paper, 2020). A tumor composed of atypical neoplastic, often pleomorphic cells that invade other tissues. "Our study has the limitation that we were not able to evaluate some genetic alterations reported in CNS GCTs, such as NF1, CBL, and FGD6, which are not covered by the Oncomine Pan-Cancer Cell-Free Assay." (PMID 32868820, 2020).
cardiovascular disease (1 paper, 2020). "The life-extending allele of the majority of the loci is associated with a reduction in cardiovascular disease phenotypes, including SNPs near the ageing loci SLC4A7, FGD6, and LINC02513 discovered in this study." (PMID 32678081, 2020).
FGD6 also shares sentences with these, for which no sentence is quoted: gastric cancer (2 papers); Alzheimer disease (1); autism spectrum disorder (1); dysplasia (1); head and neck squamous cell carcinoma (1); invasive breast carcinoma (1); neuroblastoma (1); panayiotopoulos syndrome (1).